TSPAN8 (tetraspanin 8)
Diseases named in the same sentence as TSPAN8 in open-access papers (continued):
Sharing a sentence is not in itself a finding about the gene and the disease.
gastric cancer (continued). "Studies performed on the human gastric cancer cell lines MGC‐803, AGS, MKN‐28, and BGC‐823 have shown that TSPAN8 is involved in the activation of the ERK/MAPK signaling pathway." (PMID 39031113, 2024). "Together, TSPAN8, CD151, TSPAN1, and TSPAN4 are overexpressed in gastric cancer tissues and are related to a higher clinical stage and poorer prognosis via interacting with other molecules in TEMs." (PMID 34222025, 2021). "When TSPAN8 was knocked down, the effect of EGF on promoting gastric cancer cell proliferation and invasion was attenuated." (PMID 34222025, 2021). "Specifically, TSPAN8 mediates the effect of EGF and actives the ERK MAPK pathway to promote gastric cancer cell proliferation." (PMID 34222025, 2021). "Recently, a novel study indicated a negative relationship between the expression of TSPAN8 and miR-324-5p in gastric cancer cells." (PMID 34222025, 2021). "In general, the expression of TSPAN8, CD151, TSPAN1, and TSPAN4 is increased in gastric cancer tissues and enhance the proliferation and invasion of gastric cancer cells, while CD81, CD82, TSPAN5, TSPAN9, and TSPAN21 are downregulated and suppress gastric cancer cell growth." (PMID 34222025, 2021).
glioma (10 papers, 2015 to 2025). A benign or malignant brain and spinal cord tumor that arises from glial cells (astrocytes, oligodendrocytes, ependymal cells). "In the present study, we showed that GSK621 treatment in glioma cells caused Tspan8 degradation, this could be at least one reason to explain its anti-cancer activity." (PMID 27532105, 2016). "Suppression of tetraspanin 8 expression led to reduced proliferation and migration capacity of glioma cells and increased the efficacy of temozolomide (TMZ) in vitro." (PMID 39031113, 2024). "The involvement of tetraspanin 8 in the pathogenesis of gliomas is suggested by the fact that its expression is reduced by AMP kinase whereas activation of AMP kinase leads to inhibition of cancer cell growth." (PMID 39031113, 2024). "We show that tetraspanin 8 (Tspan8) can form a complex with Rictor, which is required for mTORC2 activation and glioma cell migration." (PMID 33159013, 2020). "A recent study reported that siRNA-knockdown of Tspan8 in glioma cells reduced FAK-Y397 phosphorylation and decreased in vitro cell proliferation rate." (PMID 28188308, 2017). "GSK621 activated AMPK to inhibit mammalian target of rapamycin (mTOR) and downregulate Tetraspanin 8 (Tspan8) in glioma cells." (PMID 27532105, 2016). "Together, these results demonstrate that over-expressed Tspan8 in malignant glioma forms a complex with rictor and integrin α3 to mediate mTORC2 activation and glioma cell migration." (PMID 25761241, 2015). "In the current study, we found that Tspan8 is over-expressed in human malignant glioma tissues, as well as in several human glioma cell lines." (PMID 25761241, 2015). "Tspan8 was also over-expressed in multiple human glioma cell lines, as compared to normal brain tissues." (PMID 25761241, 2015). "Together, these results show that over-expressed Tspan8 forms a complex with integrin α3 and rictor in human glioma tissues and cell lines." (PMID 25761241, 2015). "Over-expressed Tspan8 forms a complex with rictor and integrin α3, which is required for mTORC2 activation and glioma cell migration." (PMID 25761241, 2015). "Here, using the Co-IP assay, we found that Tspan8 formed a complex with integrin α3 in the tested human glioma cell lines (CGH-5, TJ-899, SGH-44, TJ-905 and U251MG)." (PMID 25761241, 2015). "Our evidence include that Tspan8 forms a complex with mTORC2 component rictor in both human glioma tissues and cells." (PMID 25761241, 2015). "In summary, the results of this study suggest over-expressed Tspan8 in malignant glioma forms a complex with rictor and integrin α3 to regulate mTORC2 activation and glioma cell migration." (PMID 25761241, 2015). "We found that Tspan8 expression level is high in both malignant glioma tissues and in several human glioma cell lines, where it formed a complex integrin α3 and rictor, the latter is a key component of mammalian target of rapamycin (mTOR) complex 2 (mTORC2)." (PMID 25761241, 2015). "Additionally, the potential of tetraspanin 8 to activate the mTOR signaling pathway represents a promising target for the development of anticancer therapies for gliomas." (PMID 39031113, 2024). "The involvement of tetraspanin 8 in the pathogenesis of gliomas may occur through the activation of FAK kinase." (PMID 39031113, 2024). "Moreover, previously published in vitro studies have demonstrated the role of tetraspanin 8 in promoting human glioma cell lines migration through the formation of complexes with α3 integrin and Rictor protein." (PMID 39031113, 2024). "Moreover, GSK621, a novel AMP-activated protein kinase (AMPK) activator, has shown anti-cancer activity in glioma cells by the degradation of TSPAN8." (PMID 32138170, 2020). "ILK interacts with Rictor to mediate Akt-S473 phosphorylation in different cell types and Rictor may interact with Tspan8 in glioma cells." (PMID 28188308, 2017).
glioma (continued). "Our previous studies have shown that Tspan8 is over-expressed in multiple human malignant glioma tissues, as well as in human glioma cells, which forms a complex with Rictor (a mTOR component) and integrin α3 to mediate mTOR activation, cell growth, and TMZ resistance." (PMID 27532105, 2016). "In this study, Tspan8 was significantly downregulated following GSK621 treatment in glioma cells, this could explain the dramatic TMZ sensitization effect by the AMPK activator." (PMID 27532105, 2016). "AKT Thr-308 phosphorylation was also intact in Tspan8-depleted glioma cells." (PMID 25761241, 2015). "The fact that siRNA knockdown of Tspan8 or α3 integrin inhibited U251MG cell in vitro migration suggesting that Tspan8 might promote invasive behaviors of glioma cells through complex with α3 integrin." (PMID 25761241, 2015). "Here we showed that Tspan8 was over-expressed in many human glioma tissues and cell lines." (PMID 25761241, 2015). "Here, we showed that Tspan8 might serve as the potential upstream signaling for mTORC2 activation at least in glioma cells." (PMID 25761241, 2015). "Together, these results indicate that Tspan8-rictor complex might be important for mTORC2 assembly and activation as well as glioma cell migration." (PMID 25761241, 2015). "Interestingly, TSPAN8 also formed a complex with integrin α3 and Rictor in glioma cells." (PMID 38275818, 2024). "TMZ’s cytotoxicity could be significantly augmented in Tspan8-silenced glioma cells." (PMID 27532105, 2016). "In this study, we found that Tspan8 might also be involved in mTORC2 activation in glioma cells." (PMID 25761241, 2015). "Thus, we propose that Tspan8 is in complex with rictor-mTOR, which might be important for mTORC2 integrity and activation in glioma cells." (PMID 25761241, 2015). "Interestingly, Tspan8 silencing did not affect mTORC1 assembly (mTOR-Raptor association) or activation (indicated by phosphorylation of S6K1) in glioma cells." (PMID 25761241, 2015). "TSPAN8 is also important for FAK activation, forming a complex with activated FAK in primary malignant glioma tissues and glioma cell lines." (PMID 38275818, 2024). "As a result, glioma cell lines U‐87 MG and U251 MG were resensitized to TMZ, and a decrease in tetraspanin 8 expression levels was observed." (PMID 39031113, 2024). "The knockdown of TSPAN8 reduces proliferation and migration and increases the sensitivity of temozolomide (TMZ)-induced cell death and the apoptosis of glioma cells." (PMID 32138170, 2020). "TSPAN8 forms a complex with Rapamycin-insensitive companion of mammalian target of rapamycin (RICTOR), a key component of mammalian target of rapamycin complex 2 (mTORC2), and integrin α3, which are required for mTORC2 activation and glioma cell migration." (PMID 32138170, 2020).
hepatocellular carcinoma (10 papers, 2014 to 2025). A malignant tumor that arises from hepatocytes. "In this study, we explored the effects of TSPAN8 and the molecular mechanisms underlying hepatocellular carcinoma (HCC) metastasis using various HCC cell lines, tissues from 149 HCC patients, and animal models of HCC progression." (PMID 27270327, 2016). "Elevated TSPAN8 expression has been linked to enhanced invasions of hepatocellular carcinoma (HCC) cells in vitro and increased metastasis in HCC animal models." (PMID 38275818, 2024). "To date, studies have demonstrated the efficacy of monoclonal antibodies against tetraspanin 8 in hepatocellular carcinoma which strongly suggest anti‐cancer potential of this treatment." (PMID 39031113, 2024). "ADAM17 and Tspan8 are expressed in a multitude of cancers, including colorectal and hepatocellular carcinoma." (PMID 36078095, 2022). "In contrast, Tspan8 was demonstrated to correlate with metastasis of hepatocellular carcinoma, melanoma and pancreatic adenocarcinoma." (PMID 36078095, 2022). "Moreover, studies performed in a mouse model of human hepatocellular carcinoma have shown that tetraspanin 8 promotes angiogenesis, migration and metastasis of cancer cells." (PMID 39031113, 2024). "In silico assessment of transcriptomic data within the cancer genome atlas (TCGA) database indicated high expression of CD9 and CD81 in all analyzed tumor sets, while expression of TSPAN8 was elevated in particular in hepatocellular carcinoma and colonic adenocarcinoma." (PMID 36078095, 2022). "TSPAN8 is frequently found and overexpressed at both the mRNA and protein levels in hepatocellular carcinoma (HCC) and TSPAN expression is correlated with intrahepatic spreading." (PMID 32138170, 2020). "A possible role of tetraspanin 8 as a mediator of invasiveness has also been postulated and AEG‐1 protein has been suggested to regulate tetraspanin 8 expression in hepatocellular carcinomas." (PMID 39031113, 2024). "In turn, in hepatocellular carcinoma, it is assumed that tetraspanin 8 promotes invasion and formation of metastases without affecting the proliferation rate." (PMID 39031113, 2024).
non-small cell lung carcinoma (8 papers, 2019 to 2024). A group of at least three distinct histological types of lung cancer, including non-small cell squamous cell carcinoma, adenocarcinoma, and large cell carcinoma. "In lung cancer where invasive methods like transbronchial needle aspiration or transthoracic biopsy are used as the diagnosis methods, sEV markers like CD151, CD171, and tetraspanin 8 were identified as a combined diagnostic marker in 276 Non-small cell lung carcinoma (NSCLC) patients." (PMID 36612209, 2022). "Another study using proteomic analysis showed the selective enrichment of the TSPAN8 protein in EVs from metastatic NSCLC (non-small cell lung cancer) cell lines." (PMID 38275818, 2024). "CD151, CD171, and tetraspanin 8 were highly expressed in Non-Small Cells Lung Cancer (NSCLC) patients exosomes with respect to healthy donors, representing a powerful biomarker of tumor burden." (PMID 32759810, 2020). "TSPAN8 is found to be overexpressed in non-small cell lung cancer (NSCLC) cells compared with normal human bronchial epithelial cells." (PMID 32138170, 2020). "Examination of exosomes from plasma of 276 non-small cell lung cancer (NSCLC) patients shows, that CD151, CD171, and tetraspanin 8 are the strongest separators of patients with LC of all histological subtypes." (PMID 33207614, 2020). "Further, the tetraspanin-8 is significantly enriched in EVs released by metastatic non-small cell lung cancer (NSCLC) cells when compared to a non-metastatic cell line." (PMID 34830787, 2021). "Previous studies in patients with non-small cell lung cancer have shown that proteins commonly used to screen tumor biomarkers can be used as exosome biomarkers of non-small cell lung cancer, such as EGFR, CD151, CD171, tetraspanin 8, and NY-ESO-1." (PMID 30733650, 2019).
esophageal cancer (7 papers, 2012 to 2024). A primary or metastatic malignant neoplasm involving the esophagus. "In one study, exogenous expression of TSPAN8 promoted the migration/invasion of low-invasive esophageal carcinoma cell lines in vitro and their ability to invade surrounding tissues and develop lung metastasis in vivo." (PMID 38275818, 2024). "TSPAN8 is overexpressed in esophageal carcinomas and esophageal carcinoma cell lines with high-invasive potential." (PMID 32138170, 2020). "Exogenous expression of TSPAN8 promotes cell migration and invasion in esophageal carcinoma cell lines, as well as enhances the invasion and lung metastasis in esophageal tumor xenograft mouse models." (PMID 32138170, 2020). "Interestingly, TSPAN8 has been found to contribute to the migration, invasion, and metastasis of esophageal carcinoma and HCC cells by increasing the expression of a specific isoform (ADAM12m) of ADAM12, which is implicated in the metastasis of various epithelial cancers." (PMID 38275818, 2024). "In addition, tetraspanin TM4SF3/TSPAN8 promotes ADAM12 upregulation and by this esophageal carcinoma cell migration." (PMID 28260841, 2017).
ovarian carcinoma (7 papers, 2010 to 2024). A malignant neoplasm originating from the surface ovarian epithelium. "TSPAN8 was originally identified as a human tumor-associated antigen found to be overexpressed in many different epithelial cancers, including lung, liver, gastric, esophageal, colorectal, and ovarian carcinomas." (PMID 38275818, 2024). "TSPAN8 is overexpressed in epithelial ovarian cancer (EOC) tissues and correlates with poor survival." (PMID 32138170, 2020). "Additionally, the expression of tetraspanin 8 has been shown to be present in up to 52% of patients with epithelial ovarian cancer." (PMID 39031113, 2024). "In ovarian cancer, TSPAN8-LEL also performs similar functions in tumor metastasis." (PMID 34540692, 2021). "Furthermore, the monoclonal antibody TSPAN8–LEL IgG was shown to significantly reduce the incidence of epithelial ovarian cancer metastasis in vivo without causing severe toxicity." (PMID 38275818, 2024). "In vitro studies using human ovarian cancer cells SNU8, SNU251, and SK‐OV3 have shown that targeting tetraspanin 8 with monoclonal antibodies decreased cancer cell motility and invasiveness." (PMID 39031113, 2024). "TSPAN8-LEL recognized antibody shows inhibition of ovarian cancer cell metastasis both ex vivo and in vivo without severe in vitro cytotoxicity or in vivo nephrotoxicity and hepatotoxicity." (PMID 34540692, 2021). "Moreover, we found that anti-TSPAN8 IgG not only specifically inhibited the invasion of EOC cell lines, including SNU8, SNU251 and SK-OV3 cells, but also wholly and dramatically blocked ovarian cancer cell metastasis by up to around 35% with a single dose." (PMID 32138170, 2020). "For example, in ovarian cancer it is accompanied by sharp downregulation of genes COLEC11, PEG3 and TSPAN8, which is not the case in other cancers." (PMID 21047417, 2010).
prostate carcinoma (7 papers, 2015 to 2024). A carcinoma that arises from epithelial cells of the prostate gland. "TSPAN8 is also upregulated in prostate cancer tissue and associated with cell invasion." (PMID 28701765, 2017). "Several tetraspanins such as CD81, CD9, tetraspanin-6 and tetraspanin-8 were enriched in prostate cancer versus control samples." (PMID 26196085, 2015). "Furthermore, androgen was also found to induce a nuclear localization of TSPAN8, resulting in the formation of TSPAN8 and an androgen receptor (AR) complex in prostate cancer cells." (PMID 38275818, 2024).
Obesity (5 papers, 2008 to 2021). Accumulation of substantial excess body fat. "For example, the associations between TCF7L2, TSPAN8/LGR5, FTO and MetS T2D were attenuated when adjusted for BMI, suggesting the role of obesity." (PMID 26599349, 2015). "Of these core SNPs, 11 in FTO, TSPAN8, and TCF7L2 have been reported to be associated with T2D, obesity, or both, providing an independent replication of previously reported SNPs." (PMID 23626757, 2013). "MED25 was previously shown to play a critical role in the endoplasmic reticulum stress response Here, a number of the DEPs identified in the current work, including TSPAN8, SUMO3, INSL3, and MED25, were implicated in obesity-related infertility or subfertility." (PMID 34016141, 2021).
cutaneous melanoma (4 papers, 2011 to 2024). A primary melanoma arising from atypical melanocytes in the skin. "Although much is yet to be learned regarding the clinical relevance of its function, we postulate that TSPAN8 could be a promising new therapeutic target in anti-invasive therapies for cutaneous melanoma." (PMID 21081927, 2011). "Here, we show for the first time that TSPAN8 is strongly expressed in human cutaneous melanoma." (PMID 21081927, 2011). "Hence, Tspan8 may represent a promising target for both early detection and anti-invasive therapies in cutaneous melanoma." (PMID 28188308, 2017). "We demonstrate that the modulation of stiffness properties, and their correlated morphometrics, impacts cutaneous melanoma cell invasiveness following EMT switching and Tspan8 transcriptional activation." (PMID 38398085, 2024).
pancreatic ductal adenocarcinoma (4 papers, 2020 to 2025). An infiltrating adenocarcinoma that arises from the epithelial cells of the pancreas. "They expressed several tetraspanins, which are involved in the regulation of stemness in other cell types, including Tspan8 that is upregulated by SOX9 in pancreatic ductal adenocarcinoma in response to EGF stimulation." (PMID 37408269, 2023). "In a pancreatic ductal adenocarcinoma model, a Siglec-4 spacer CAR targeting a membrane proximal (TSPAN8) epitope was efficiently engaged in vitro, while a membrane distal (CD66c) epitope did not activate the T cell." (PMID 32849600, 2020).
Crohn disease (3 papers, 2010 to 2018). A gastrointestinal disorder characterized by chronic inflammation involving all layers of the intestinal wall, noncaseating granulomas affecting the intestinal wall and regional lymph nodes, and transmural fibrosis. "Although the study identified three associated CNV loci—HLA for Crohn’s disease, rheumatoid arthritis and type 1 diabetes; IRGM for Crohn’s disease; and TSPAN8 for type 2 diabetes, all of which were tagged by SNPs from previous GWAS." (PMID 30060490, 2018).
liver cancer (3 papers, 2017 to 2025). An epithelial or non-epithelial malignant neoplasm that arises from the liver. "The findings from our screen offer new insights into the transcriptional regulation of TSPAN8 in liver cancer and may have broader implications for understanding its role in cancer progression." (PMID 40801599, 2025). "Moreover, knockout of NF2, DYRK1A, and SOX9 in another TSPAN8-expressing human liver cancer cell line, SNU878, similarly resulted in a downregulation of TSPAN8." (PMID 40801599, 2025). "We tested this strategy in the liver cancer cell lines MEC and JHH5, which express endogenous TSPAN8 and have been engineered to stably express Cas9." (PMID 40801599, 2025). "For example, tetraspanin-8 was found to be overexpressed in intrahepatic spreading HCC and might be involved in hematogenous intrahepatic metastasis of liver cancer cells." (PMID 29029515, 2017).
lung adenocarcinoma (3 papers, 2021 to 2024). A carcinoma that arises from the lung and is characterized by the presence of malignant glandular epithelial cells. "SOX21-AS1 predicts prognosis and potentiates proliferation in lung adenocarcinoma, and its silencing represses migration and invasion by regulating GATA6, which decreases the levels of TSPAN8." (PMID 34511042, 2021).